BRAF (B-Raf proto-oncogene, serine/threonine kinase)
Diseases named in the same sentence as BRAF in open-access papers (continued):
Sharing a sentence is not in itself a finding about the gene and the disease.
ameloblastoma (continued). "On the contrary, other factors, such as sex, histological variants, and recurrence, were insignificant among ameloblastoma cases with BRAF V600E mutation." (PMID 36428683, 2022). "Heterogeneity was significant for the pooled prevalence of BRAF mutation among ameloblastoma, which had a p < 0.05 in Cochrane Q statistics, and I2 statistics values of 83.09%." (PMID 36428683, 2022). "Molecular targeted therapy drugs that have the potential to be used in ameloblastoma are those which inhibit the functions of mutated BRAF and MEK." (PMID 36127985, 2022). "Our findings showed that the younger generation (less than 54 years old) was associated with BRAF V600E mutation in ameloblastoma patients." (PMID 36428683, 2022). "The current study profiled the relationship between the mutation of BRAF V600E and the incidence of ameloblastoma." (PMID 36428683, 2022). "Regarding the ameloblastomas, the mutations have been detected only in BRAF wild-type samples (P = 0.038)." (PMID 35468886, 2022). "This study reported a 70.49 % mutation prevalence with the BRAF V600E gene among ameloblastoma patients." (PMID 36428683, 2022). "In line with reports about other neoplasms that harbor a malignant counterpart, the frequency of the BRAF p.V600E mutation is higher in ameloblastoma (64% in conventional, 81% in unicystic, and 63% in peripheral) than in ameloblastic carcinoma (35%)." (PMID 36378285, 2022). "The finding of high mutation of BRAF V600E indicates the need to explore the molecular pathogenesis of ameloblastoma." (PMID 36428683, 2022). "A study on ameloblastoma cell lines has reported an in vitro sensitivity of BRAF inhibitor (vemurafenib) to hinder V600E mutation." (PMID 36428683, 2022). "This meta-analysis outcome of high prevalence has shown that BRAF V600E mutation has played a role in molecular pathogenesis in ameloblastoma incidence." (PMID 36428683, 2022). "The BRAF V600E mutation remains the most critical molecular marker studied in ameloblastoma pathogenesis." (PMID 36428683, 2022). "There was also a case report which was ameloblastoma initially but later presented with ameloblastic carcinoma; positive BRAF V600E mutation was subsequently detected." (PMID 36428683, 2022). "In these case series, this targeted therapy to BRAF mutated ameloblastomas revealed a significant response." (PMID 35055392, 2022). "From 17 studies that reported total BRAF mutation cases, the overall pooled prevalence among ameloblastoma based on QEM was 70.49% (95% CI = 62.20–78.19%; p < 0.05)." (PMID 36428683, 2022). "This meta-analysis shows that BRAF V600E mutation has a high pooled prevalence of 70.49% in ameloblastoma." (PMID 36428683, 2022). "The ameloblastoma cell line AM1 had been shown harboring BRAF(V600E) mutation in previous studies, which was also confirmed in our investigation." (PMID 35055392, 2022). "Based on this result, we suggest a correlation between odontogenesis and BRAF V600E mutation, which led to the ameloblastoma incidence." (PMID 36428683, 2022). "Out of 432 conventional ameloblastoma cases, 316 (73.15%) had BRAF mutation, while other variants (including unicystic, desmoplastic, and peripheral) reported that 80.33% (98 out of 122 patients) also had the mutation." (PMID 36428683, 2022). "A large proportion of ameloblastomas harbor BRAF(V600E) mutation, the BRAF inhibitor with or without the combination of MEK inhibitor was applied in several cases of unresectable or recurrent ameloblastoma harboring BRAF(V600E) mutation." (PMID 35055392, 2022). "BRAF V600E mutation has a significant association with a broad range of neoplasms, and in ameloblastoma specifically." (PMID 36428683, 2022). "A case report of a 29-year-old woman with a recurrence of ameloblastoma with BRAF V600E mutation, who received vemurafenib, was symptomless and had tumour shrinkage after 11 months of therapy." (PMID 36428683, 2022).
ameloblastoma (continued). "Though rare, high rates of BRAF p.V600E hotspot mutation (33.3–82%) have enticed growing interest for BRAF-targeting, as ameloblastoma often requires extensive facial surgeries, compromising quality-of-life, yet, frequently recurs." (PMID 35296678, 2022). "Other histological variants were also reported with the same range of BRAF V600E mutation with conventional ameloblastoma: 82.11% mutation in unicystic, 62.50% in desmoplastic, and 66.67% mutation in peripheral ameloblastoma." (PMID 36428683, 2022). "The present systematic review and meta-analysis show that BRAF V600E mutation has a high pooled prevalence of 70.49% in ameloblastoma." (PMID 36428683, 2022). "This systematic review and meta-analysis aim to pool the overall mutation prevalence of BRAF V600E in reported ameloblastoma cases and to determine its association with patient demographic and clinicopathological features." (PMID 36428683, 2022). "Recent advances of molecular biology unraveled that recurrent BRAF(V600E) activating mutation is the most common genetic aberration in ameloblastomas, however, the detailed tumorigenic molecular mechanism is yet to be fully elucidated." (PMID 35055392, 2022). "BRAF(V600E)-mutated ameloblastoma cases showed significantly more SOX2-positive cells (24.5%) than in wild type (6.6%) (p < 0.05)." (PMID 35055392, 2022). "As a result, the meta-analysis revealed a significant association between BRAF V600E mutation and young and adult age groups among ameloblastoma patients." (PMID 36428683, 2022). "We also demonstrated that knockdown of SOX2 leads to decreased viability of ameloblastoma cells, and increased expression of SOX2 was associated with resistance to anti-BRAF small molecule inhibitors, vemurafenib and dabrafenib, in ameloblastoma cells." (PMID 35055392, 2022). "The NCT02367859 trial also reported a stable disease for a BRAF p.V600E-mutated ameloblastoma patient." (PMID 35296678, 2022). "Recently, two studies performed whole-exome sequencing to assess coding mutations in ameloblastomas and reported uncommon mutations in several other genes occurring in the background of BRAF p.V600E mutation." (PMID 35048058, 2021). "Ameloblastic carcinomas, the malignant counterpart of ameloblastomas, also harbor BRAF p.V600E mutations, but with reported frequencies varying from 25 to 40%." (PMID 35048058, 2021). "Currently, the evidence is still insufficient to draw any conclusions about further mutations other than BRAF p.V600E participating as drivers of ameloblastoma pathogenesis." (PMID 35048058, 2021). "In line with the reports about other neoplasms that harbor a malignant counterpart, the frequency of BRAF p.V600E mutation is higher in ameloblastoma (64% in conventional, 81% in unicystic, and 63% in peripheral) than in ameloblastic carcinoma (35%)." (PMID 35048058, 2021). "It is worth noting that the lower frequency of BRAF p.V600E mutation in ameloblastic carcinomas compared with ameloblastomas is similar to what is observed in other benign tumors and their malignant counterparts." (PMID 35048058, 2021). "Previous studies have demonstrated that a missense somatic mutation on BRAF (V600E) frequently happened in Ameloblastoma." (PMID 33395399, 2021). "Among them, SMO mutations have been detected in between 13 and 39% of ameloblastomas, occurring in a mutually exclusive pattern with BRAF p.V600E." (PMID 35048058, 2021). "While the BRAF p.V600E mutation emerged as a molecular signature for ameloblastomas and has also been shown to be frequent in other tumors with ameloblastic differentiation, KRAS codon 12 mutations seem to be a marker of adenomatoid odontogenic tumors." (PMID 35048058, 2021). "Ameloblastic carcinomas also have been reported to have BRAF V600E mutations similar to that seen in ameloblastomas alluding to the possibility that ACs arise from ameloblastomas." (PMID 33736630, 2021).
ameloblastoma (continued). "BRAF-V600E is the most common mutation, which is associated with clinical and molecular behavior of ameloblastoma." (PMID 33680332, 2021). "In 2014, the pioneer study by the group of Heikinheimo reported for the first time recurrent activating BRAF p.V600E mutations in ameloblastomas." (PMID 35048058, 2021). "The mutational screening of BRAF by molecular assays has been shown to be useful for the differential diagnosis between unicystic ameloblastomas and odontogenic cysts." (PMID 35048058, 2021). "Mutations in genes that belong to the mitogen-activated protein kinase (MAPK) pathway are present in almost 90% of ameloblastomas, with BRAF V600E, being the most described mutation." (PMID 35048068, 2021). "We highlighted the correlation between BRAF V600E immunoexpression and molecular analysis of this mutation in ameloblastomas." (PMID 32388526, 2020). "Taking into consideration new scientific discoveries on the molecular pathogenesis of ameloblastoma, we are the first to have performed BRAF mutation analysis in an EAC patient." (PMID 32643344, 2020). "The present study reported the highest frequency of BRAF V600E mutation in ameloblastomas (92%) compared with the previous studies till now." (PMID 32388526, 2020). "We recently reported that 10 out of 11 patients with calcifying cystic odontogenic tumors (calcifying odontogenic cyst) have mutations in the CTNNB1 gene, while 12 out of 14 patients with ameloblastoma have mutations in the BRAF gene." (PMID 32113465, 2020). "Association between BRAF V600E mutation and clinicopathologic features and behavior of ameloblastoma remains controversial." (PMID 32388526, 2020). "In recent years, with the rapid development of molecular biology, some studies also reported a BRAF-V600E mutation rate of approximately 60% in ameloblastoma." (PMID 33176823, 2020). "Mutation in BRAF gene-valine (V) to glutamic acid (E) substitution at codon 600 is a common mutation in ameloblastoma." (PMID 32388526, 2020). "We report the highest frequency (92%) of BRAF V600E mutation in ameloblastomas in the Iranian population." (PMID 32388526, 2020). "This study aimed to evaluate BRAF V600E gene mutation and expression of its related proteins with clinicopathologic parameters in conventional ameloblastoma." (PMID 32388526, 2020). "BRAF mutation is also associated with ameloblastoma invasiveness, and our results also demonstrated that BRAF-V600E is associated with AC." (PMID 33176823, 2020). "We also studied the correlation between BRAF V600E mutation and clinicopathologic parameters of conventional ameloblastoma." (PMID 32388526, 2020). "The correlation between BRAF V600E mutation and aggressiveness of ameloblastoma remains conflicting." (PMID 32388526, 2020). "In the present study, we reported the highest frequency of BRAF V 600E (92%), which is reported in the literature in the Iranian population mutation ameloblastomas." (PMID 32388526, 2020). "To the best of our knowledge, we report the highest frequency of BRAF V600E mutation in ameloblastomas which is reported yet as 82% by Diniz." (PMID 32388526, 2020). "In the head and neck region, BRAF gene mutations are detected at a high frequency in ameloblastomas, and this was also confirmed not only by genetic analysis but also by immunohistochemistry using a BRAF V600E-mutant specific antibody." (PMID 32113465, 2020). "There are some in vitro studies that have described the sensitivity of BRAF inhibitors in ameloblastoma cells with BRAF V600E mutation." (PMID 32388526, 2020). "In this study, we sought to uncover the molecular basis of ameloblastoma and to determine the cellular phenotype of ameloblastoma cells with BRAF mutations." (PMID 32096304, 2020). "BRAF inhibition has proved to be an efficient strategy in patients with a BRAF-mutated ameloblastoma." (PMID 31340860, 2019).
ameloblastoma (continued). "The BRAF V600E mutation of ameloblastomas was associated with a younger age of onset, with the tumor located in the mandible, and later recurrences, whereas BRAF wild-type tumors arose more frequently in the maxilla and showed earlier recurrences." (PMID 31340860, 2019). "Recent advances about molecular pathogenesis of ameloblastoma determine that a great percentage show BRAF V600E mutations." (PMID 29670736, 2018). "Peripheral type ameloblastomas revealed exclusively single somatic mutations in BRAF or SMO (rho − 0.224, p = 0.010)." (PMID 29388014, 2018). "Strikingly, all ameloblastomas with BRAF mutations were exclusively located in the mandible with the exception of one single case (97.1%)." (PMID 29388014, 2018). "Using this method, it was discovered that mutations in the SMO gene encoding smoothened protein was commoner in maxillary ameloblastomas, while BRAF V600E mutations were commoner in mandibular ameloblastomas." (PMID 28592923, 2017). "On the other hand, we found that BRAF Val600Glu appeared to be the only mutation in most ameloblastoma cases (86%, 12/14)." (PMID 28658279, 2017). "The BRAF Val600Glu mutation was detected in 12 of 14 ameloblastomas, confirming the prevalence of this mutation." (PMID 28658279, 2017). "Recently, several mutations in genes along the Ras-BRAF pathway were identified by next-generation sequencing to be frequently associated with ameloblastoma." (PMID 28658279, 2017). "In ameloblastoma samples, a Val600Glu mutation in BRAF was found in 5 of 7 cases, and a Gln61Arg mutation in NRAS was found in the other two cases." (PMID 28658279, 2017). "BRAF p.V600E mutations commonly are identified in conventional and unicystic ameloblastoma." (PMID 40893989, 2025). "Our findings expand the known role of BRAF p.V600E mutations beyond ameloblastomas." (PMID 41364259, 2025). "Future ameloblastoma studies in the United States can incorporate genetic analysis, which may shed insight into how the BRAF V600E mutation can affect the development and recurrence of ameloblastomas in multi- and mixed-racial populations." (PMID 38607614, 2025). "In the present case we report a AKT1 c.49G > A p.(Glu17Lys) exon 4 variant, a hotspot mutation which is commonly associated with various cancers, including breast, colorectal and lung, but has also been recently identified in an ameloblastoma with a BRAF mutated background." (PMID 41144131, 2025). "In addition, the BRAF V600E mutation is associated with up to 90% of ameloblastomas, and possibly related to recurrent tumors." (PMID 38607614, 2025). "The majority of ameloblastomas have been demonstrated to have BRAF V600E mutations." (PMID 38461286, 2024). "Different studies have reported mutations in BRAF V600E in ameloblastomas." (PMID 38615253, 2024). "The results presented in this study may represent another reference supporting the use of targeted therapies for MAPK pathway mutations mainly BRAF V600E for the treatment of ameloblastomas." (PMID 38615253, 2024). "Also, to the best of our knowledge, our study represents the second largest series evaluating BRAF V600E mutation in ameloblastomas specifically derived from Latin American services." (PMID 38615253, 2024). "However, the joint senescence impact of the BRAF mutation and BRAFi in the setting of ameloblastoma is probably followed by an effect of autophagy, which is likely associated with further squamous differentiation of cells." (PMID 39621130, 2024). "In ameloblastomas, BRAF is the most frequently mutated gene, having a mutation rate of 63%." (PMID 39430655, 2024). "The prevalence of the BRAF V600E immunoexpresion may suggest the feasibility of utilizing BRAF-targeted therapy for ameloblastomas with this mutation." (PMID 38615253, 2024). "However, further well-designed cohort studies are needed to verify the association of the BRAF V600E mutation in ameloblastoma before applying new medical interventions." (PMID 39274556, 2024).
ameloblastoma (continued). "Thus, we currently see a very low use of BRAF inhibitors in V600E-mutated ameloblastoma in the literature." (PMID 37115331, 2023). "This difference suggests that BRAF expression may occur earlier in the tumorigenesis of ameloblastomas, and additional mutations may be acquired during tumor evolution." (PMID 38021761, 2023). "The outcomes of this study may prove valuable in distinguishing patients with ameloblastoma who have developed BRAF-V600E gene mutations, and help clinicians make treatment decisions without resorting to invasive testing." (PMID 37646022, 2023). "Therefore, BRAF inhibitor therapy should at least be considered in the treatment of ameloblastoma if the mutation is detected, especially in view of the fact that there is no standard therapy for metastatic ameloblastoma." (PMID 37115331, 2023). "Therefore, the objective of this study is to develop a radiomics-based model that predicts the BRAF-V600E gene mutation status in patients with ameloblastoma." (PMID 37646022, 2023). "However, in the analysis, a lower number of acanthomatous ameloblastoma cases were reported with the BRAF V600E mutation compared to unicystic ameloblastoma." (PMID 38021761, 2023). "In maxillary ameloblastomas, additional mutations included BRAF L597R, FGFR2, PIK3CA, and SMO." (PMID 38021761, 2023). "Alternatively, unicystic ameloblastoma may be a precursor neoplasia of ameloblastoma, with mutated BRAF present from the beginning of the pathology." (PMID 38021761, 2023). "Significant mutation of BRAF V600E in mandibular ameloblastoma may allow for better risk assessment and the possibility of personalized adjunctive therapy to sustain jaw functionality." (PMID 36428683, 2022). "Besides, two other recurrent BRAF p.V600E-mutated ameloblastoma patients have also responded dramatically to dabrafenib monotherapy." (PMID 35296678, 2022). "In this study, we sorted out the expression patterns of SOX2+ and Ki-67+ cells in dental follicle and ameloblastoma, confirmed a high rate of BRAF(V600E) mutation of ameloblastomas in Asian patients, and these mutated cases showed significantly more SOX2-positive cells." (PMID 35055392, 2022). "Several findings indicated that the SOX2 expressing cells played significant roles in propagation and recurrence of ameloblastoma and suggested BRAF(V600E) mutation may contribute to the expansion of SOX2-positive cell compartment." (PMID 35055392, 2022). "However, further well-designed cohort studies are needed to verify the association of BRAF V600E mutation in ameloblastoma before applying new medical interventions." (PMID 36428683, 2022). "The 40.4% (19/47) of ameloblastomas harbored the BRAF V600E mutation." (PMID 35468886, 2022). "The BRAF V600E mutation was revealed only in ameloblastoma samples." (PMID 35468886, 2022). "However, AMCas harbor BRAF p.V600E mutations like other ameloblastoma-related tumors, with varying prevalence from 25 to 40%." (PMID 36378285, 2022). "It has been shown that this mutated BRAF V600E is commonly found in ameloblastoma of the mandible." (PMID 36428683, 2022). "Face preservation therapy could be achieved in pediatric patients presenting with BRAF V600E mutated ameloblastoma." (PMID 36127985, 2022). "Therefore, we suggest that future research on a meta-analysis related to comparing the validated methods to detect BRAF V600E mutation in ameloblastoma." (PMID 36428683, 2022). "The discovery that ameloblastoma has a high mutation incidence of BRAF V600E may enable a better investigation of pathophysiology." (PMID 36428683, 2022). "Although targeted therapy has mainly focused on ameloblastomas, further in vitro and in vivo studies, and clinical trials may help to establish standardized therapeutic regimens both for ameloblastomas and other BRAF mutation-positive odontogenic tumors." (PMID 35048058, 2021).